DGCR8 (DGCR8 microprocessor complex subunit)
Diseases named in the same sentence as DGCR8 in open-access papers (continued):
Sharing a sentence is not in itself a finding about the gene and the disease.
thyroid nodule (1 paper, 2024). A small circumscribed mass in the THYROID GLAND that can be of neoplastic growth or non-neoplastic abnormality. "In conclusion, we provide an overall mutational frequency of DICER1 and DGCR8 mutations in a bi-institutional cohort of thyroid nodules, showing that these mutations are rare events in FTs." (PMID 38252873, 2024).
tonsillar cancers (1 paper, 2016). "Subsequent QRT-PCR measurement of Drosha, Dicer1, DDX5 and DGCR8 indicated a general overexpression of all four biogenesis components in tonsillar cancers." (PMID 26867589, 2016).
tuberculosis (1 paper, 2023). A chronic, recurrent infection caused by the bacterium Mycobacterium tuberculosis. "The SNV rs720012 in DGCR8 has been previously associated with non-muscle-invasive bladder cancer, tuberculosis susceptibility, and increased risk of pre-eclampsia." (PMID 36968598, 2023).
Vestibular schwannoma (1 paper, 2025). A vestibular schwannoma (also known as acoustic neuroma, acoustic neurinoma, or acoustic neurilemoma) is a benign, usually slow-growing tumor that develops from the VIIIth cranial nerve supplying the inner ear. "Three genes centromeric to NF2 on 22q have now been found shown to account for ~ 70% of familial and ~ 30% of sporadic patients with multiple non-vestibular schwannomas: SMARCB1, LZTR1, and much less commonly DGCR8." (PMID 41160189, 2025).
virus infection (1 paper, 2019). "Interestingly, Dgcr8-/- cells were more resistant to virus infection than Dicer-/- cells, which supports a dual function for DICER by also acting as a direct antiviral factor targeting viral transcripts for degradation by RNAi." (PMID 31012846, 2019).
vitiligo (1 paper, 2025). Generalized well circumscribed patches of leukoderma that are generally distributed over symmetric body locations and is due to autoimmune destruction of melanocytes. "For the first time, we demonstrate that the Dicer rs1057035 polymorphism is associated with vitiligo susceptibility, and the downregulation of Drosha, DGCR8, and Dicer suggests their potential roles as biomarkers in the pathogenesis of vitiligo." (PMID 40837640, 2025). "In our study, no significant statistical differences were observed between vitiligo patients and controls regarding the frequencies of Drosha and DGCR8 gene polymorphisms in the Turkish population." (PMID 40837640, 2025). "Therefore, we aimed to analyze the association between the expression levels of miRNA machinery genes (Drosha, DGCR8, Dicer) and SNPs (Drosha rs493760, DGCR8 rs1640299, Dicer rs1057035) in three key components of miRNA machinery genes and the risk of vitiligo." (PMID 40837640, 2025). "Therefore, downregulated expressions of Drosha, DGCR8, and Dicer in vitiligo patients may decrease such miRNAs and increase susceptibility to vitiligo." (PMID 40837640, 2025). "In conclusion, our study provides the first evidence that downregulated expression levels of Drosha, DGCR8, and Dicer may be involved in vitiligo pathogenesis, and that the Dicer rs1057035 polymorphism may contribute to increased susceptibility to vitiligo in the Turkish population." (PMID 40837640, 2025). "Due to their essential roles in miRNA maturation, we focused on the polymorphisms and gene expression profiles of Dicer, Drosha, and DGCR8, which act upstream in the miRNA biogenesis pathway, in patients with vitiligo compared to healthy controls." (PMID 40837640, 2025). "Correlation analysis of the relative expression levels of Drosha, DGCR8 and Dicer genes in the total 111 research objects from vitiligo and control groups was performed using Spearman's rank correlation analysis." (PMID 40837640, 2025). "We believe that it is important to investigate these Drosha, DGCR8, and Dicer SNPs and expressions for the first time in vitiligo." (PMID 40837640, 2025). "Our results showed that Drosha, DGCR8, and Dicer were significantly downregulated in vitiligo patients compared to controls." (PMID 40837640, 2025). "The relative expression levels of Drosha, DGCR8 and Dicer in vitiligo patients compared with the control subjects." (PMID 40837640, 2025). "ROC analysis showed that low expressions of Drosha, DGCR8, and Dicer could distinguish vitiligo cases from healthy controls, suggesting that these genes may be potential biomarkers for accurate diagnosis of vitiligo." (PMID 40837640, 2025). "Drosha, DGCR8, and Dicer in the vitiligo patient group were in Hardy-Weinberg equilibrium (p>0.05)." (PMID 40837640, 2025).
cancer (53 papers, 2009 to 2025). A tumor composed of atypical neoplastic, often pleomorphic cells that invade other tissues. "Mutations in DROSHA or DGCR8 impair Microprocessor complex function, leading to a global reduction in miRNA levels in various cancers." (PMID 41154621, 2025). "The Cancer Genome Atlas (TCGA) database was also probed for DICER1/DGCR8 mutations and miRNA dysregulation." (PMID 38252873, 2024). "Although in other types of cancer where E518K mutation is found, other mutations affecting DGCR8 are described." (PMID 38607000, 2024). "This has been reported in cancers with mutations in the miRNA processing machinery, specifically in DGCR8 and DICER." (PMID 34885022, 2021). "In summary, we performed a systematic review on the association between DROSHA and DGCR8 polymorphisms and risk of cancer." (PMID 29654164, 2018). "And accumulating researches have focussed on the associations between the DGCR8 polymorphisms and cancer risk." (PMID 29654164, 2018). "We comprehensively reviewed and analyzed the effect of DROSHA and DGCR8 polymorphisms on cancer risk." (PMID 29654164, 2018). "Three of them (DROSHA rs10719, rs6877842, and DGCR8 rs417309) were revealed to be associated with risk of cancer in whole population or some particular subgroups." (PMID 29654164, 2018). "Our aim is to explore the association of DROSHA and DGCR8 SNPs with cancer risk, supplying clues to researchers for screening novel cancer biomarkers." (PMID 29654164, 2018). "Our findings demonstrated that the rs417309 SNP in DGCR8 was significantly associated with an elevated risk of overall cancer in every genetic model." (PMID 29654164, 2018). "In the present study, total seven SNPs in DROSHA and DGCR8 genes were comprehensively reviewed and analyzed to estimate their associations with the risk of overall cancer." (PMID 29654164, 2018). "Single nucleotide polymorphisms (SNPs) in miRNA biosynthesis genes DROSHA and DGCR8 were indicated to be correlated with cancer risk." (PMID 29654164, 2018). "Second, studies of DROSHA and DGCR8 polymorphisms on cancer predisposition field remain emerging, which resulted in limited number of the relevant investigations." (PMID 29654164, 2018). "The rs417309 G/A polymorphism was the most extensively investigated one amongst DGCR8 SNPs, and the rs417309-A allele was strongly associated with an elevated cancer susceptibility." (PMID 29654164, 2018). "Complementary members of the miR biogenesis pathway, including Drosha, DGCR8, and Argonaute-2, have been implicated in cancer." (PMID 27356752, 2016). "While a role of canonical Drosha/DGCR8-dependent miRNAs in human diseases is well recognized, there is much to be learned about the implications of mirtronic miRNAs in cancer development and their possible diagnostic potential." (PMID 27019673, 2016). "The DGCR8 (G > A; rs417309) variant was the most extensively investigated polymorphism in this gene, and the rs417309-A allele was strongly associated with increased cancer susceptibility." (PMID 36672288, 2023). "The risk allele rs417309-A could elevate DGCR8 expression level, probably through interrupting miRNA binding, thus facilitating the cancer development." (PMID 29654164, 2018). "Thus far, accumulating studies have been concerned with the association between DROSHA and DGCR8 SNPs and the susceptibility to cancer." (PMID 29654164, 2018). "Collectively, these studies highlight the pivotal role of DGCR8 as a pri-miRNA processing factor involved in both neuronal development and cancer progression." (PMID 40243428, 2025). "SUMOylation at Lys707 stabilizes DGCR8 and improves its pri-miRNA binding capacity, promoting cancer cell migration and transformation." (PMID 41154621, 2025). "These include mutations in DROSHA, DGCR8, and DICER1 in cancer, and recently identified AGO mutations in neurodevelopmental disorders." (PMID 40243428, 2025).
cancer (continued). "Hence, single nucleotide polymorphism (SNP) in DROSHA and DGCR8 genes can affect their structure or expression, resulting in incomplete miRNA processing influencing the expression of the target gene, thereby acting as a risk factor for cancer that will be further discussed." (PMID 38607000, 2024). "The high expression of DGCR8 was shown to promote the occurrence, development, and metastasis of cancer, including in TC." (PMID 38607000, 2024). "It has been reported that TGF-β, a cytokine with an important role in promoting proliferation and metastasis in some types of cancers, is positively regulated by DGCR8." (PMID 38607000, 2024). "Pooling the data from 45 articles, our results reveal the association of DROSHA (A > G; rs10719), DGCR8 (G > A; rs417309), RAN (A > G; rs3803012), and GEMIN3 (C > A; rs197414) with a 19–93% higher susceptibility to overall cancer." (PMID 36672288, 2023). "In human cancers, mutations in DROSHA, DGCR8, and DICER1 are associated with several types of cancer." (PMID 37179717, 2023). "In several cancers, such as colorectal cancer and ovarian cancer, upregulation of DGCR8 was found, suggesting an oncogenic role for this protein." (PMID 36497229, 2022). "Taken together, these results demonstrate a critical role of OC cell-intrinsic WTAP in promoting cancer cell progression by regulating DGCR8-miR-200." (PMID 35733918, 2022). "Downregulation of miRNA processing genes (Dicer and several other proteins including Drosha, TARBP2, DGCR8 and XPO5) is an important cause for reduced levels of mature miRNAs in some cancer cells." (PMID 33917769, 2021). "Impaired miRNA processing by knockdown of Drosha, DGCR8, or Dicer can reduce steady-state miRNA levels and enhance the proliferation and motility of cancer cells." (PMID 33846300, 2021). "Taken together, these results suggest that DGCR8 positively regulates cancer cell radioresistance independently of its Drosha-binding ability." (PMID 34188037, 2021). "DGCR8 is a major component of microprocessor that can be SUMOylated at two distinct sites K259 and K707 exhibiting opposite functions in cancer cells." (PMID 32333719, 2020). "The expression level of DGCR8, another component of the microprocessor, has been found to be increased in various human cancers, including oesophageal, bladder, prostate, and ovarian cancers." (PMID 32138313, 2020). "Our study generalized the status quo of the current studies on cancer-related polymorphisms in DROSHA and DGCR8 genes, supplying investigators with novel clues for identifying new biomarkers with cancer-forewarning function." (PMID 29654164, 2018). "KHSRP is also a very important component of the Drosha/DGCR8 complex, and here we for the first time found that KHSRP SUMOylation was also linked to tumorigenesis and cancer progression." (PMID 29020972, 2017). "In this study, a meta-analysis was conducted to evaluate the association between SNPs in five genes (DROSHA, DGCR8, XPO5, RAN, and DICER1) involved in the canonical microRNA biogenesis pathway and human cancer risk." (PMID 27957388, 2016). "In summary, this meta-analysis suggests a potential role of the miRNA biogenesis genes DGCR8 (rs417309 G>A) and DICER1 (rs1057035 T>C) in cancer risk." (PMID 27957388, 2016). "Because the expression pattern of DGCR8 and Drosha in cancer is still controversial, further studies are necessary to elucidate the mechanisms whereby their expression patterns influence cancer pathways related to miRNA processing in the nucleus." (PMID 26308063, 2015). "DROSHA and DGCR8 can be either upregulated or downregulated in cancers, often depending on the cancer type, which suggests the tissue- and cell-specificity of miRNAs and the diverse roles they play in cancer development." (PMID 41154621, 2025).
cancer (continued). "The biogenesis of miRNAs is a tightly regulated multistep process involving enzymes such as Drosha, DiGeorge syndrome critical region gene 8 (DGCR8), exportin-5, Dicer, and Argonaute (AGO) proteins, where disruption in these pathways is associated with various pathologies, including cancers." (PMID 40843353, 2025). "The lncRNA Uc.283 + A promotes cancer progression by blocking the binding of DGCR8 and pri-miR-195." (PMID 36841801, 2023). "Bioinformatics analysis of CLIP-seq data from ENCORI database further found that splicing factor DGCR8 could bind to KRT4 mRNA in cancer cells." (PMID 36811004, 2023). "The co-factor of Drosha, DGCR8, can also be affected in cancer." (PMID 36497229, 2022). "Among them, TNRC6, DGCR8, C17ORF85, ZC3H7B, SFRS1 and TIA1, were obviously positively associated with XIST in ≥3 cancers; while eIF4AIII, FXR1, FXR2 and C22ORF28 were significantly negatively correlated with XIST in ≥3 cancers." (PMID 36212008, 2022). "This notion, in effect, has been tested in some studies performed concerning DGCR8 in cancers." (PMID 32246817, 2020). "Moreover, cancer is supported by altered expression levels of miRNA processing machinery components such as Drosha, DGCR8, and Dicer that are down-regulated or up-regulated in several cancers." (PMID 33330058, 2020). "Studies have revealed the up-regulation of DGCR8 expression in various cancers." (PMID 29654164, 2018). "In conclusion, the DROSHA rs10719, rs6877842 SNPs, and DGCR8 rs417309 SNP play pivotal roles in cancerogenesis and may be potential biomarkers for cancer-forewarning." (PMID 29654164, 2018). "Analysis of associations between SNPs from DROSHA, DGCR8, XPO5, RAN, and DICER1 and cancer risk." (PMID 27957388, 2016). "The results demonstrated that the GG genotype of rs417309 in DGCR8 was significantly rarer among cases compared with controls in the overall pooled analysis and the TT genotype of rs1057035 in DICER1 was associated with a 13% increase in cancer risk." (PMID 27957388, 2016). "As DGCR8 is abnormally expressed in diverse cancers and phosphorylation of DGCR8 can promote cell growth and migration, we wondered whether K707-SUMOylation of DGCR8 is connected with tumorigenesis and tumor cell migration." (PMID 26202964, 2015). "Dysregulation of DGCR8 and Drosha have been reported to play significant roles in cancer." (PMID 26308063, 2015). "Aberrantly high expression of DGCR8 is also observed in cancer." (PMID 26308063, 2015). "Deregulation of miRNAs in various cancers may be related with altered expression and function of the genes involved in the miRNA machinery components, including DGCR8 and AGO2." (PMID 23775303, 2014). "A possible explanation for this distinction comes from our previous observation that components of the microRNA biosynthetic pathway (i.e. the microprocessor complex (DGCR8 and Drosha)) are up-regulated in B-cell malignancies (including MM) but down-regulated in T-cell malignancies." (PMID 21592325, 2011). "Dgcr8 levels are differentially regulated during development and in cancers." (PMID 19759829, 2009). "However, the findings were inconsistent and there was no systematic analysis for DROSHA and DGCR8 SNPs and cancer risk." (PMID 29654164, 2018). "Moreover, correlations with cancer risk could also be observed in stratified analyses of DROSHA rs10719, rs6877842 SNPs and DGCR8 rs417309 SNP." (PMID 29654164, 2018). "Additionally, it was shown that the expression of DGCR8 was upregulated in several types of cancer." (PMID 26688807, 2015). "Interestingly, some cancers have decreased, while other cancers have increased levels of Dgcr8." (PMID 19759829, 2009). "Recent studies have uncovered the crucial role of DGCR8 in pri‐miRNA processing and how it often necessitates METTL3 or METTL14 in different cancer types." (PMID 38380598, 2024).
cancer (continued). "These cancers also depend on a set of hemoproteins, such as cytochrome c-1 (CYC1), succinate dehydrogenase complex subunit C (SDHC) for cellular respiration, and DGCR8 for microRNA biogenesis, each of which uses heme as a co-factor." (PMID 38649187, 2024). "The second most recurrently altered TAD boundary (chr22:19600000–19675000) was flanked by active and low-active TADs, and is adjacent to TADs containing the cancer genes SEPTIN5, DGCR8, and HIRA." (PMID 38758740, 2024). "We analyzed the mRNA expression levels of miRNA machinery components (DROSHA, DGCR8, XPO5, RAN, DICER, TARBP2, and AGO2) utilizing mRNA-Seq data from The Cancer Genome Atlas (TCGA) and The Genotype-Tissue Expression (GTEx) projects." (PMID 39404265, 2024). "The expression of DGCR8 in benign tumours was significantly different from NTAT and malignant tumours." (PMID 36499151, 2022). "Impaired miRNA processing caused by the aberrant expression of miRNA biosynthesis genes DGCR8 and DROSHA can noticeably promote tumorigenesis, being correlated with pathophysiology of cancers." (PMID 36499151, 2022). "Knock-down of DGCR8 results in, as observed upon DROSHA deplete on, a pronounced decrease in mature miRNA level affecting the expression of cancer-related genes." (PMID 36499151, 2022). "In recent years, increasing studies have confirmed that m6A methylation‐related genes, such as ALKBH5, FHL2, DGCR8, YTHDF2, YTHDF3, and PICM8, were overexpressed in tumor tissues and closely related to malignant tumors." (PMID 33264518, 2021). "The microRNA (miRNA) expression levels are globally suppressed in human cancer compared to those in normal tissues, which are mostly contributed to genetic and epigenetic alterations in miRNA-processing machinery components such as DROSHA, DGCR8, XPO5, TARBP2, DICER, and AGO2 in human cancer." (PMID 30305728, 2019). "Moreover, pan-cancer studies have identified significant variations in the expression of miRNA-processing genes, including DICER1, DGCR8, and TARBP2, across multiple malignancies, reinforcing the importance of miRNA biogenesis defects in neoplastic progression." (PMID 41463093, 2025). "Accumulating evidence indicates that some cancers and tumor cells are characterized by reductions in the levels of mature miRNAs compared to normal tissues or cells, which is due to reduced expression of Dicer and several other miRNA processing proteins (Drosha, TARBP2, DGCR8 and XPO5)." (PMID 33917769, 2021). "Five genes are involved in DNA repair, a role closely related to genome maintenance and cancer, and were shown to have a protective role in various types of cancer (only one paper is cited by gene, but many others confirm this role): EXO1, ERCC1, GTF2H1, MDC1, and DGCR8." (PMID 31568528, 2019). "We eliminated 83 records after browsing the titles and abstracts (40 were functional studies; 12 were reviews or meta-analysis; 9 were not case–control studies; 52 were unrelated to DROSHA or DGCR8 SNPs; 8 were unrelated to cancer; 12 were not correlated with cancer risks)." (PMID 29654164, 2018). "Moreover, for carcinoma cases, we did not observe any significant association between DROSHA, DGCR8, DICER, TARBP2, or PRKRA mRNA levels and clinical–histopathological parameters such as gender, age, tumor size, or presence of metastasis (data not shown)." (PMID 23671264, 2013).